LZTFL1 (leucine zipper transcription factor like 1)
Diseases named in the same sentence as LZTFL1 in open-access papers (continued):
Sharing a sentence is not in itself a finding about the gene and the disease.
COVID-19 (continued). "The transcriptome analysis of lung biopsies from patients with COVID-19 showed the presence of signals associated with epithelial-mesenchymal transition of lung cells (EMT) or pulmonary fibrosis, which is regulated by LZTFL1, suggesting that this locus may serve as a potential therapeutic target." (PMID 39364016, 2024). "LZTFL1 regulates airway ciliogenesis,34 which is critical for virus clearance from airways, suggesting insufficient SARS-CoV-2 virus clearance in airways with patients carrying rs11385942 risk allele may lead to the progression of COVID-19 disease severity." (PMID 34998241, 2022). "In addition to ABO blood type, receptors, and immune genes, GWAS studies on COVID-19 have revealed the association of SLC6A20 (rs2271616), LZTFL1 (rs10490770, rs11385942, rs73064425), and DPP9 (rs2109069) genes with respiratory failure caused by COVID-19 infection and critical illness." (PMID 36292769, 2022). "Finally, the AncestryDNA COVID-19 host genetic study identified COVID-19 genetic associations with SLC6A20, LZTFL1 variants on the chromosome, ABO locus on chromosome 9 and a novel association on chromosome 11 that includes Polypeptide N-Acetylgalactosaminyltransferase 18 (GALNT18)." (PMID 34575070, 2021). "The introgressed variants of the LZTFL1 (A block) were significantly associated with a higher risk of hospitalization for COVID-19 in our population (patients vs. controls), and a higher risk of critical COVID-19 compared to less severe hospitalized patients who did not require support in the ICU." (PMID 41302157, 2025). "Our present study analysing COVID-19 GWAS loci led to the identification of LZTFL1 and RAVER1 as influencing COVID-19 disease severity." (PMID 34998241, 2022). "Our genome-wide analysis of pneumonia and severe COVID-19 point to two overlapping regions (defined by linkage disequilibrium analysis), both of which include SLC6A20 and LZTFL1 genes." (PMID 35910207, 2022). "Known significant loci for COVID-19 severity in 3p21.31 (near SLC6A20 and LZTFL1) and 21q22.11 (in IFNAR2) were clearly replicated at genome-wide significance in this study, specifically for risk of infection, hospitalization and severity." (PMID 35708486, 2022). "Our analysis revealed a strong signal of coherence between COVID-19 and M05B medications, with chemokine receptor genes CCR1, CCR3 and LZTFL1 as lead hits." (PMID 36156592, 2022). "For the MR analysis on transcripts, expression levels of two genes, LZTFL1 and SLC4A10, showed robust MR evidence on COVID-19 severity using data from GenOMICC." (PMID 35772218, 2022). "Several other loci show no previously documented genome-wide significant associations, despite the high significance and attractive candidate genes for COVID-19 (for example, CXCR6, LZTFL1, IFNAR2 and OAS1/OAS2/OAS3 loci)." (PMID 34237774, 2021). "However, more functional studies are required to better understand how rs17713054 influences LZTFL1 expression and EMT process in the context of COVID-19 severity." (PMID 38956433, 2024). "CCRL2, LZTFL1, SCAP, and SACM1L are also differentially expressed in at least one experiment that measures differential expression of genes in lung tissues and related cell lines infected with COVID-19 or other viruses that stimulate similar immune responses." (PMID 36763080, 2023). "Finally, two GWAS have identified the loci 3p21.31 (LZTFL1, SLC6A20, CCR9, FYCO1, CXCR6, and XCR1) and 9q34.2 (ABO) with COVID-19 severity." (PMID 33868239, 2021). "A recent genome-wide association study (GWAS) reported that two polymorphisms, the rs11385942 insertion/deletion polymorphism of the leucine zipper transcription factor-like protein 1 (LZTFL1) gene and the rs657152 SNP of the ABO gene, are related to severe COVID-19 cases with respiratory failure." (PMID 33396837, 2020).
COVID-19 (continued). "Thus, it leads to the interaction of the enhancer with the promoter of the LZTFL1 gene at the 3p21.31 locus, consequently, upregulation of LZTFL1 occurs and, the epithelial-mesenchymal transition (EMT) process is suppressed which suggests exacerbating the COVID-19 outcome." (PMID 38956433, 2024). "Given that LZTFL1 may not be the only gene involved in COVID-19 vulnerability, our data implicating FYCO1 as an additional monocyte candidate gene of the chromosome 3 GWAS susceptibility locus also deserve further consideration." (PMID 35648852, 2022). "deleted this portion of LZTFL1 using a genome editor CRISPR/Cas9 in blood cell lines and found that the expression of CCR9 and SLC6A20 was affected by the locus, suggesting that this COVID-19 GWAS locus at chromosome locus 3p21.21 may influence different genes depending on cell type." (PMID 34998241, 2022).
respiratory failure (13 papers, 2020 to 2025). The significant impairment of gas exchange within the lungs resulting in hypoxia, hypercarbia, or both, to the extent that organ tissue perfusion is severely compromised. "Different human polymorphisms have an impact on clinical outcomes: sequence changes in ApoE, TLR7, TMEM189-UBE2V1, as well as SLC6A20, LZTFL1, CCR9, FYCO1, CXCR6, XCR1, have been associated with severe disease outcomes as well as respiratory failure." (PMID 35207458, 2022).
breast carcinoma (10 papers, 2019 to 2026). "Together, these results implicated that miR-21/LZTFL1 axis might promote breast cancer EMT via β-catenin." (PMID 31351450, 2019). "LZTFL1 is targeted by miR-21, leading to the promotion of breast cancer proliferation and metastasis." (PMID 38807590, 2024). "miR-21 promotes breast cancer progression and metastasis due to its suppression of LZTFL1, which acts on the beta-catenin protein signaling pathway, inactivating the epithelial-mesenchymal transition." (PMID 38813102, 2024). "Specifically, miR-21 was shown to contribute to breast cancer proliferation and metastasis by targeting LZTFL1." (PMID 36980974, 2023). "Previous studies demonstrated that miR-21 targets LZTFL1 in breast cancer cells, RASA1 in colon cancer cells, and KLF5 in hepatocellular carcinoma cells." (PMID 37547633, 2023). "Down-regulation of miR-21 was found to inhibit EMT-mediated metastasis of breast cancer in vitro and in vivo by promoting LZTFL1 expression via the miR-21/LZTFL1/β-catenin axis." (PMID 33477629, 2021). "Survival analysis of LZTFL1 levels in breast cancer prognosis was estimated with the Kaplan–Meier method by log-rank test according to data from the Cancer Genome Atlas." (PMID 31351450, 2019). "Analysis based on TCGA database also suggests that low expression of LZTFL1 predicts a poor outcome in breast cancer." (PMID 31351450, 2019). "LZTFL1 siRNA and miR-21 inhibitor were co-transfected to breast cancer cells, then cell proliferation, migration and epithelial–mesenchymal transition (EMT) makers were tested." (PMID 31351450, 2019). "In conclusion, our results suggest that the miR-21/LZTFL1/β-catenin/EMT axis promotes metastasis via EMT process in breast cancer." (PMID 31351450, 2019). "We confirmed that miR-21 promotes cell proliferation, metastasis, and tumor progression in breast cancer, while knockdown of LZTFL1 reverses these effects." (PMID 31351450, 2019). "In our study, we also found that LZTFL1 prevents breast cancer progression by inhibition of the EMT." (PMID 31351450, 2019). "According to the breast cancer data acquired with the TCGA platform, we found that lower expression of LZTFL1 is related to shorter overall survival in breast cancer." (PMID 31351450, 2019). "Mechanically, miR-21/LZTFL1 axis promotes the nuclear translocation of β-catenin which actives EMT process in breast cancer." (PMID 31351450, 2019). "MiR‐21 also promoted breast cancer proliferation and metastasis by targeting the LZTFL1 gene." (PMID 41241871, 2026). "miR-21 promoted the proliferation and metastasis of breast cancer cells by targeting LZTFL1." (PMID 35154284, 2022). "However, the mechanisms of the miR-21/LZTFL1 axis in regulating breast cancer metastasis remain to be determined." (PMID 31351450, 2019). "Therapies that result in re-expression of LZTFL1 or inhibition of miR-21 might be promising new approaches to targeted therapy for breast cancer." (PMID 31351450, 2019). "Therefore, the function of miR-21 in promoting breast cancer progress is due, in significant part, to its suppression on LZTFL1." (PMID 31351450, 2019). "Furthermore, an in vivo study also demonstrated that the miR-21/LZTFL1 axis regulates the EMT to promote metastasis in breast cancer." (PMID 31351450, 2019). "Targeting miR-21/LZTFL1/β-catenin/EMT axis might be a promising strategy in breast cancer therapy." (PMID 31351450, 2019). "Down-regulation of miR-21 inhibits breast cancer cell proliferation and EMT-mediated metastasis in vitro and in vivo by promoting LZTFL1 expression." (PMID 31351450, 2019). "Knockdown of LZTFL1 overcame the suppression of miR-21 inhibitor on cell proliferation, metastasis and the expression of EMT markers in breast cancer cells." (PMID 31351450, 2019).
Obesity (5 papers, 2019 to 2024). Accumulation of substantial excess body fat. "Lztfl1−/− mouse embryonic fibroblasts (MEFs) have significantly longer cilia than wild-type MEFs, and global Lztfl1 deficiency results in pleiotropic phenotypes, including obesity, also observed in the Lztfl1−/− mouse model." (PMID 37239474, 2023). "It has been recently shown that the deletion of LZTFL1 can cause pleiotropic defects in mice, including obesity." (PMID 34073493, 2021). "Clinically, BBS patients are characterized with non-sense mutations of LZTFL1/BBS17 display obesity, polydactyly, diabetes, renal abnormalities, hypogenitalism, hypertension, cognitive impairment, and retinal degeneration." (PMID 31293455, 2019). "Interestingly, this work links obesity to the expression of LZTFL1 in the brain and demonstrates that the loss of this protein specifically in the brain can lead to leptin resistance." (PMID 34073493, 2021). "Mutations in LZTFL1 have been reported in human BBS patients, which develop a wide range of pathologies, including obesity, which is so far one of the comorbidities with a stronger link to both COVID-19 infection and severity." (PMID 34073493, 2021). "LZTFL1-null mice show the phenotype of obesity, retinal degeneration, and abnormal cilia development." (PMID 31293455, 2019). "Recently, LZTFL1 knockout mice was well established, which showed the phenotype of obesity, retinal degeneration, and abnormal cilia development." (PMID 31293455, 2019). "The correlation between rs17713054 SLC6A20-LZTFL1 and obesity is supported by previous research indicating that LZTFL1 may regulate leptin signaling, and participate in the LepRb signaling pathway in the hypothalamus, which controls energy homeostasis." (PMID 39175753, 2024). "Notably, Lztfl1 knockout mice exhibit hyperphagia, leptin resistance, and obesity." (PMID 39175753, 2024). "LZTFL1-null mice displayed pleiotropic phenotypes, which are commonly observed in BBS, including retinal degeneration and obesity." (PMID 31293455, 2019).
Bardet-Biedl syndrome (4 papers, 2019 to 2023). A ciliopathy with multisystem involvement. "LZTFL1/BBS17 is a member of the Bardet-Biedl syndrome (BBS) and encodes a protein involved in protein trafficking to primary cilia." (PMID 34073493, 2021). "Leucine zipper transcription factor like 1 (LZTFL1) is a member of the Bardet–Biedl syndrome gene family." (PMID 31293455, 2019). "Leucine zipper transcription factor like 1 (LZTFL1), also called BBS17, is a member of the Bardet–Biedl syndrome (BBS) gene family." (PMID 31293455, 2019). "LZTFL1 is also known as BBS17 that interacts with a BBS (Bardet-Biedl Syndrome) protein complex known as the BBSome and may act as a cargo protein to regulate ciliary trafficking of the BBSome." (PMID 36966254, 2023).
gastric cancer (3 papers, 2017 to 2024). A primary or metastatic malignant neoplasm involving the stomach. "The tumor suppressor Leucine zipper transcription factor-like 1 (LZTFL1) in gastric cancer can also inhibit β-catenin nuclear translocation to suppress the metastasis of gastric cancer cells." (PMID 39404930, 2024). "Previously we found that LZTFL1 can suppress gastric cancer metastasis by regulating β-catenin signal and suppress lung tumorigenesis, possibly affecting epithelial cell identity and/or EMT." (PMID 36966254, 2023). "Previously we identified a tumor suppressive function of LZTFL1 in gastric cancer and showed that LZTFL1 can suppress gastric cancer cell migration and invasion through regulating nuclear translocation of β-catenin." (PMID 36966254, 2023). "Leucine zipper transcription factor-like 1 (LZTFL1) has been identified as a novel tumor suppressor in gastric cancer." (PMID 28430641, 2017).
asthma (2 papers, 2024 to 2025). "In the case of patients having asthma, the only significant correlation was found for the presence of the LZTFL1 minor variant and the hospitalization of these patients." (PMID 39752416, 2025).
lung carcinoma (2 papers, 2021 to 2022). "Leucine zipper transcription factor-like 1 (LZTFL1) inhibits lung cancer tumorigenesis, at least partly by inhibiting HH signaling pathway to maintain epithelial cell differentiation." (PMID 35433472, 2022).
pneumonia (2 papers, 2022 to 2023). An acute, acute and chronic, or chronic inflammation focally or diffusely affecting the lung parenchyma, caused by an infection in one or both of the lungs (by bacteria, viruses, fungi, or mycoplasma.). "Specifically, through a univariate regression analysis, we evaluated the association between risk allele carrier status for each genetic variant (OAS1/2/3, DPP9, IFNAR2, LZTFL1, ABO, and FUT2) and the development of clinical complications and of pneumonia." (PMID 36873632, 2023).
Breast tumor (1 paper, 2019). "Breast tumor growth, metastasis and the expression of EMT markers or LZTFL1 were detected in vivo." (PMID 31351450, 2019).
colorectal carcinoma (1 paper, 2019). A malignant epithelial neoplasm that arises from the colon or rectum and invades through the muscularis mucosa into the submucosa. "Colocalization studies illustrated that the expression of LZTFL1 overlapped with that of E-cadherin at the plasma membrane in differentiated normal colonic epithelial cells, and this colocalization was absent in colorectal carcinomas due to the loss of LZTFL1 protein expression." (PMID 31293455, 2019).
kidney cancer (1 paper, 2023). Primary or metastatic malignant neoplasm involving the kidney. "LZTFL1 is a tumor suppressor located in chromosomal region 3p21.3 that is deleted frequently and early in various cancer types including the kidney cancer." (PMID 36966254, 2023). "Reactivation or re-expression of LZTFL1 in ccRCC may have clinical significance in kidney cancer therapy." (PMID 36966254, 2023).
kidney chromophobe (1 paper, 2023). "LZTFL1 was significantly downregulated in 8 tumor types compared to normal tissues, including kidney clear cell carcinoma (KIRC) and kidney chromophobe (KICH)." (PMID 36966254, 2023).
kidney tumor (1 paper, 2023). "Furthermore, we tested the role of LZTFL1 in kidney tumor cell growth both in vitro and in vivo through gain and loss-functional studies." (PMID 36966254, 2023). "In this work, we hypothesized a tumor suppressive function of LZTFL1 in ccRCC and its mechanism of action based on extensive bioinformatics analysis of public patients’ tumor data and validated it using both LZTFL1 gain- and loss-functional studies in kidney tumor cell lines and PDX model systems." (PMID 36966254, 2023). "Our studies showed that LZTFL1 inhibits kidney tumor cell growth and cell cycle G1 to S phase transition." (PMID 36966254, 2023). "Taken together, these results suggest that the effect of LZTFL1 on the AKT protein stability is mediated through ZNRF1, which is at least partially responsible for the anti-cell proliferative function of LZTFL1 on kidney tumor cells." (PMID 36966254, 2023). "Our studies indicated that LZTFL1 inhibits kidney tumor cell proliferation by destabilizing AKT through ZNRF1-mediated ubiquitin proteosome pathway and inducing cell cycle arrest at G1." (PMID 36966254, 2023). "Mechanistically, we found that LZTFL1 inhibits kidney tumor cell cycle progression and suppresses the AKT signaling by destabilizing AKT via ZNRF1-mediated ubiquitin proteosome pathway (UPP)." (PMID 36966254, 2023). "Our data show that LZTFL1 inhibits kidney tumor cell growth both in vitro and in vivo." (PMID 36966254, 2023). "We found that LZTFL1 inhibited G1 to S phase cell cycle progression in kidney tumor cells." (PMID 36966254, 2023). "That being said, other mechanisms by which LZTFL1 inhibits kidney tumor cell proliferation may also be important as knockdown of ZNRF1 only partially reversed the effect of LZTFL1 on tumor cell growth." (PMID 36966254, 2023). "Furthermore, clinically, we found that downregulation of LZTFL1 in ccRCC may correlate with worse outcome and may be used as a prognostic maker; and overexpression of LZTFL1 in kidney tumors may be a therapeutic strategy against ccRCC." (PMID 36966254, 2023). "As LZTFL1 did not impact the transcription of AKT in kidney tumor cells and the GO suggested that LZTFL1 may be involved in proteasomal protein catabolic process and ubiquitination, we tested whether LZTFL1 regulates the stability of AKT." (PMID 36966254, 2023).
polyp (1 paper, 2023). A usually exophytic mass attached to the underlying tissue by a broad base or a thin stalk. "The gene LZTFL1 is involved in cilia inhibition, and shows a higher expression in polyp mucosa of CRSwNP patients." (PMID 37085563, 2023).
renal clear cell carcinoma (1 paper, 2023). "H&E staining confirmed the pathological type of the tumors harvested from PDX model as renal clear cell carcinoma and IHC analysis revealed that AKT expression was decreased in the LZTFL1 treated group." (PMID 36966254, 2023).
viral infection (1 paper, 2025). "LZTFL1, a gene expressed in lung epithelial cells and located in chromosomal region 3p21.3, plays a vital role in regulating the epithelial-mesenchymal transition, a key response pathway to viral infection." (PMID 40543387, 2025).